INS (insulin)
Diseases named in the same sentence as INS in open-access papers (continued):
Sharing a sentence is not in itself a finding about the gene and the disease.
diabetes (continued). "Background/Objectives: The objective was to analyze the effects of Dipeptidyl Peptidase-4 (DPP-4) inhibitors on glycemic control, insulin dose, and preservation of β-pancreatic function (C-peptide) in patients with type 1 diabetes mellitus (T1DM)." (PMID 41590243, 2026). "KPD is characterised by unprovoked, transient, index episodes of diabetic ketoacidosis, often in the absence of markers of islet cell autoimmunity, with frequent subsequent insulin independence and diabetes remission." (PMID 41770244, 2026). "In type 2 diabetes mellitus, positive correlations were also seen between both an exaggerated glucagon response and an estimate of insulin resistance." (PMID 41292690, 2026). "A total of 428 patients diagnosed with diabetes mellitus and undergoing insulin therapy were enrolled from four selected hospitals in Dar es Salaam." (PMID 41628120, 2026). "A study by Wondmkun stated that it was important to understand the impairment of insulin signaling which was related to obesity-induced diabetes to help discover better pharmacological treatment strategies and to help in prevention of obesity and T2D." (PMID 41601869, 2026). "Glucose-insulin dynamics can be predicted accurately and efficiently using the model in clinical settings for diabetes management." (PMID 41551260, 2026). "On average, the surgery group was younger, had higher BMI, larger abdominal sagittal diameter, higher glucose, HbA1c and insulin levels, and higher prevalence of diabetes compared to the control group." (PMID 41490246, 2026). "Technosphere® insulin (Afrezza®; Mannkind Corporation, Danbury, CT, USA) is the only available inhaled insulin that has regulatory approval for the treatment of adult individuals with diabetes mellitus and has been available for more than a decade." (PMID 41798548, 2026). "In summary, the involvement of LRRC8A in cell volume regulation and insulin signaling makes it an integral part of various aspects of diabetes." (PMID 41439137, 2026). "This form of diabetes shows clinical characteristics intermediate between type 2 and type 1 diabetes, presenting both insulin resistance and an insulin secretory defect that often requires earlier initiation of insulin therapy." (PMID 41635418, 2026). "Numerous research groups have explored diverse approaches to generate functional insulin-producing beta-cells for diabetes management in both animal models and human subjects; however, these efforts have yet to yield definitive therapeutic success." (PMID 41597265, 2026). "In this age group the use of diabetes technology (glucose sensors, insulin pumps and automated insulin dosage, AID) is recommended." (PMID 42162463, 2026). "Biomedical applications are discussed with a focus on dermal and transdermal drug delivery, particularly insulin delivery for diabetes management as well as wound repair, regenerative therapies, photodynamic treatments, and biosensing." (PMID 42005999, 2026). "Non-invasive insulin development has been one of the highly researched fields in diabetes management." (PMID 41798548, 2026). "In Sub-Saharan Africa, adolescents and young adults with T1D face challenges including limited healthcare infrastructure, inadequate disease awareness, restricted access to insulin and diabetes supplies, and high out-of-pocket costs." (PMID 41841472, 2026). "The patients were examined for the prevalence of diabetes (severity levels: diet, oral antidiabetic drugs, and insulin) and severe periodontitis (≥30% of teeth with ≥5 mm of proximal attachment loss)." (PMID 41789954, 2026). "Our findings are consistent with another research conducted in Malaysia where insulin users scored relatively low in diabetes knowledge despite receiving education on injection techniques and glucose monitoring." (PMID 41311517, 2026). "Prior to admission, her diabetes treatment consisted of linagliptin (5 mg/day), mitiglinide (20 mg/day), and 4 units of insulin degludec/insulin aspart (IDeg/Asp) injections in the morning." (PMID 41536580, 2026).
diabetes (continued). "During her hospital stay, she developed nausea, vomiting, and metabolic abnormalities consistent with euglycemic diabetic ketoacidosis (eDKA), necessitating intensive care management with dextrose-containing fluids, insulin, and electrolyte correction." (PMID 42116991, 2026). "Diabetes mellitus is a multifaceted metabolic disorder characterized by chronic hyperglycemia, arising from defects in insulin secretion, insulin action, or both." (PMID 41578487, 2026). "Type 2 diabetes mellitus has central complications: Diabetes, a metabolic disorder primarily characterized by hyperglycemia due to insufficient insulin secretion, or impaired insulin signaling, has significant central complications." (PMID 40819304, 2026). "The system demonstrated basal release under normoglycemic conditions and enhanced release under hyperglycemic conditions, offering potential for closed-loop insulin delivery in diabetes management." (PMID 41346708, 2026). "In this review, we discuss strategies for obtaining insulin-producing cells from diverse cellular sources, summarize the latest advances in stem cell-based diabetes therapy, and propose future research directions." (PMID 42104727, 2026). "After five months, a repeat OGTT showed improvement, shifting from the level of diabetes to impaired glucose tolerance, with substantially reduced insulin levels." (PMID 42022705, 2026). "This study investigates the effects of sinapine on glycogen synthesis and lipid metabolism in insulin‐resistant HepG2 cell models and type 2 diabetes mellitus (T2DM) mice." (PMID 41497732, 2026). "The implementation of a BPA within the discharge navigator resulted in a remarkably high rate of appropriate insulin prescriptions (99 %) and a high provision of necessary diabetes supplies (88 %) for patients seen by a DCES during their hospitalization." (PMID 41551323, 2026). "Long-term insulin treatment, which effectively normalized blood glucose for over 15 weeks, significantly attenuated this diabetes-induced KIM-1 shedding (p < 0.05)." (PMID 41601953, 2026). "Background/Objectives: Diabetes mellitus is a serious global disease characterized by chronic hyperglycemia, resulting from defects in insulin secretion, insulin action, or both." (PMID 41599697, 2026). "Automated insulin delivery proved effective in addressing the peculiar challenges of pancreatogenic diabetes, including high glycemic variability and a more complex management of prandial insulin therapy." (PMID 41635418, 2026). "Diabetes mellitus (DM) is a chronic metabolic disorder characterized by insufficient insulin action and persistent hyperglycemia, leading to serious macrovascular and microvascular complications." (PMID 41519856, 2026). "Background and Objectives: Diabetes mellitus represents one of the most prevalent chronic metabolic disorders worldwide, necessitating precise insulin dose management to prevent both acute and long-term complications." (PMID 41901583, 2026). "We report the case of a 25-year-old woman with a 2-year history of type 1 diabetes mellitus who was initially treated with insulin detemir and insulin glulisine." (PMID 42255890, 2026). "Mice with β-cell-specific knockout of the essential autophagy gene Atg7 exhibit reduced β-cell mass, abnormal insulin secretory granules, defective insulin secretion, and ultimately develop overt diabetes." (PMID 41601937, 2026). "In the diabetes cohort, treatment adjustments involving OADs and insulin are made at each clinical visit, with decision timepoints based on patient visits." (PMID 39792998, 2026). "Empagliflozin and sitagliptin are commonly co-administered to manage type 2 diabetes mellitus due to their complementary mechanisms of action on renal glucose reabsorption and insulin secretion, respectively." (PMID 42162103, 2026). "Ensuring accurate prescriptions for insulin and diabetes supplies is critical for safe transitions of care." (PMID 41551323, 2026).
diabetes (continued). "Early insulin therapy, for example, is particularly effective in patients with β-cell-dysfunction-driven diabetes, whereas GLP-1-supported weight reduction and glitazone therapy are more suitable for insulin-resistance-driven diabetes." (PMID 42042596, 2026). "Poor knowledge, attitudes and practices regarding insulin therapy remain a major barrier to optimal glycemic control in patients with type 2 diabetes mellitus." (PMID 42282382, 2026). "Isolated Diabetes: Primarily caused by defects in the functional machinery of the β-cell (e.g., KCNJ11, ABCC8, INS)." (PMID 41614934, 2026). "The participants were inpatients with diabetes who had been receiving insulin injections for more than 1 month." (PMID 42079401, 2026). "A PubMed search using the keywords "insulin", "edema" and "diabetes" identified 1380 articles, from which 32 reports of insulin edema cases documented in English were reviewed in detail and summarized in this table." (PMID 41476905, 2026). "The authors gathered data from a comprehensive review of existing research on neddylation in diabetes, including studies on insulin signaling, glucose and lipid metabolism, and related diseases." (PMID 41492274, 2026). "Card9 silencing markedly increased diabetes incidence and reduced survival, accompanied by decreased insulin secretion." (PMID 41243316, 2026). "The association between SHR and sepsis was significantly modified by diabetes mellitus, BMI, and insulin use (all P for interaction<.05)." (PMID 41996634, 2026). "Herein, we report a case of capivasertib-induced diabetes successfully managed with insulin-independent glucose-lowering agents while capivasertib therapy was continued." (PMID 42022705, 2026). "This instability carries significant cost implications: some individuals spend over $1,000 USD per month on insulin, and these high prices influence one in six Americans with diabetes to ration their insulin supplies." (PMID 41726984, 2026). "Diabetes mellitus (DM) is a chronic disease in which glucose metabolism is altered due to increased resistance to insulin action or low insulin production." (PMID 41564321, 2026). "JNK3 is crucial for β-cell function and survival, influencing incretin response and insulin secretion, making it a potential therapeutic target for diabetes." (PMID 41480766, 2026). "This work paves the way for rapid, low-cost bedside monitoring of insulin to improve the diagnosis and management of diabetes and also expands the generality of the robust split-luciferase sensor system to include phage display-solubilized receptors." (PMID 41696271, 2026). "Our initiative aims to further enhance the insulin and diabetes-supply prescription accuracy for all patients evaluated by a DCES." (PMID 41551323, 2026). "METHODS: We conducted a pilot single-center observational study involving patients aged ≥ 75 years with insulin-treated diabetes who met the French national criteria for CGM reimbursement." (PMID 41840510, 2026). "In that report, decreased insulin secretion in type 1 diabetes mellitus, but exaggerated insulin response in type 2 diabetes mellitus, was correlated with the exaggerated glucagon response to the arginine challenge test." (PMID 41292690, 2026). "Metformin, an insulin-sensitizing agent widely used in the management of diabetes, has emerged as a potential adjunctive therapy for mitigating AAWG, although real-world clinical data remain limited." (PMID 41988244, 2026). "All together, these publications describe 19 individuals, all with insulin-treated permanent neonatal diabetes and/or pancreatic agenesis." (PMID 41500078, 2026). "These interactions are further complicated by metabolic conditions such as obesity and diabetes, where hormonal resistance (e.g., leptin, insulin) and neurotransmitter dysregulation contribute to altered taste preferences and compulsive eating behaviors." (PMID 41659336, 2026).
diabetes (continued). "Diabetes mellitus is a metabolic disorder characterized by hyperglycemia, which occurs due to problems in insulin secretion, insulin action, or both, and remains a major global health burden." (PMID 42254168, 2026). "Diabetes duration was ≥ 10 years in 62%, 41% received insulin treatment before infection, 80% had HbA1c ≥ 7%, 12% had albumin < 2.5 g/dL, and 75% had hemoglobin < 8 g/dL." (PMID 41564031, 2026). "We introduce an expert-guided XAI framework to improve the transparency and trustworthiness of deep learning models for insulin titration in diabetes management." (PMID 41748914, 2026). "Disruption of any component can impair insulin secretion, contributing to the pathophysiology of diabetes." (PMID 41424854, 2026). "The SGLT2 inhibitor was discontinued, and the patient was transitioned to a basal-bolus insulin regimen with structured diabetes education." (PMID 42005196, 2026). "Diabetes mellitus (DM) is a metabolic disorder marked by persistent hyperglycemia (HG), resulting from abnormalities in insulin secretion or insulin resistance." (PMID 41742733, 2026). "The results showed that sympathetic denervation alone accelerated T1D progression, as evidenced by increased diabetes incidence and mortality, reduced serum insulin levels, enhanced immune cell infiltration, and decreased islet area." (PMID 41243316, 2026). "Diabetes mellitus encompasses a heterogeneous group of metabolic disorders defined by abnormalities in insulin secretion, function, or both." (PMID 41597265, 2026). "The main factors considered during the matching process included insulin delivery and glucose monitoring systems, duration of diabetes, shared hobbies, life stage, and age." (PMID 41564292, 2026). "Continuous glucose monitoring and AI facilitate the integration of the three pillars of metabolic control: nutrition, exercise, and insulin, optimizing diabetes treatment and opening new perspectives in its management." (PMID 41596449, 2026). "Supporting evidence shows modest weight loss improves metabolic health by reducing liver and pancreatic fat, with reductions in hepatic fat and improved insulin sensitivity leading to diabetes remission." (PMID 41036672, 2026). "Type 1 diabetes mellitus (T1D) has been recognized as a chronic autoimmune disease for five decades, but therapy has relied on the exogenous replacement of insulin, which is an imperfect substitute for normal β cell function." (PMID 42138080, 2026). "One way of managing type 1 diabetes mellitus is by using insulin pumps for continuous insulin delivery instead of insulin bolus regimens." (PMID 41198916, 2026). "Diabetes Mellitus is a chronic metabolic disorder characterized by impaired insulin production and/or action, leading to persistent hyperglycemia and insulin resistance." (PMID 41977405, 2026). "This population often has cardiovascular complications and is more likely to have diabetes due to impaired insulin secretion or insulin resistance." (PMID 41321955, 2026). "Reducing the monitoring time would likely facilitate the presence of additional diabetes-related variables (e.g., carbohydrate intake, or insulin administration)." (PMID 40585404, 2025). "Diabetes mellitus (DM) is a metabolic disorder resulting from impaired insulin secretion, defective insulin action, or a combination of both." (PMID 41369400, 2025). "More importantly, in AD, the deficits in brain insulin and insulin resistance correspond to the characteristics observed in type 1 diabetes mellitus (T1DM) and T2DM, respectively." (PMID 39966707, 2025). "Diabetes medications included insulin (39.1%) and oral hypoglycaemic agents [sulfonylureas (n = 189; 23.6%), dipeptidyl peptidase-4 inhibitors (n = 249; 31.1%) and metformin (n = 481; 60.0%)]." (PMID 39916475, 2025). "BAs are considered a potential cell source for treating metabolic diseases such as diabetes as their increased activity also contributes to insulin sensitivity in patients with diabetes." (PMID 40926989, 2025).
diabetes (continued). "The rapid advancement of digital health technologies—such as continuous glucose monitors, automated insulin delivery systems, and telehealth platforms—has transformed diabetes management." (PMID 41409447, 2025). "The aim of this study was to assess the impact of socioeconomic deprivation on access to diabetes technology, specifically insulin pumps, and its outcome in children with type 1 diabetes." (PMID 40718276, 2025). "The relationship between RyR dysfunction and the development of impaired insulin secretion in diabetes is assessed, noting their limited role in human diabetes pathogenesis given the disease’s polygenic nature." (PMID 40422193, 2025). "Diabetes is a condition where the body struggles to manage blood sugar levels due to issues with insulin, a hormone produced by the pancreas." (PMID 40855115, 2025). "The introduction of this technology revolutionized the treatment of diabetes and sparked the development of modern insulin analogues, such as the fast-acting Humalog (1996) and the long-acting Lantus (2000)." (PMID 40574081, 2025). "Type 1 diabetes mellitus (T1DM) is a chronic autoimmune disease characterized by the destruction of the insulin‐producing pancreatic β cells, leading to a loss of insulin secretion and subsequent hyperglycemia." (PMID 40501403, 2025). "Animal models suggest that diabetes arises from impaired glucose-stimulated insulin secretion and a reduction in beta-cell mass." (PMID 41323015, 2025). "We included the most recent available dataset from each country in the analysis for a total of 79 countries sampling 4,837 people with diabetes using insulin across the time periods 2007–2020." (PMID 40245017, 2025). "Diabetes mellitus is a group of metabolic diseases characterized by hyperglycemia resulting from defects in insulin action, insulin secretion, or both." (PMID 41158621, 2025). "In mouse models of obesity and diabetes, they reduce adiposity, increase energy expenditure, and improve glucose and insulin homeostasis." (PMID 40862756, 2025). "This study assessed insulin administration knowledge among diabetes patients in Kathmandu Valley, revealing that although most demonstrated adequate knowledge, critical gaps remain in expiry checks, insulin types, and postinjection care." (PMID 41306599, 2025). "Our diabetes team’s short-term goal—especially for the CDCESs—is to help guardians learn how to adjust insulin doses to meet glycemic targets." (PMID 41283065, 2025). "Hyperglycemia and alterations in insulin secretion and sensitivity are, along with beta cell death, the hallmarks of diabetes." (PMID 40559375, 2025). "In STZ-induced diabetes of this rodent, the insulin level was increased, and the plasma glucose level was decreased by short-term i.p. injection of 5 mg/kg body weight of 20E." (PMID 40136680, 2025). "The active constituents, including lovastatin and monene chemicals, can enhance insulin production from pancreatic β-cells and elevate insulin levels, thus addressing metabolic disorders such as hyperlipidemia and diabetes." (PMID 40564947, 2025). "The clinical definition of diabetic ketoacidosis can be summarized as an acute condition of uncontrolled diabetes requiring immediate insulin and intravenous fluid therapy." (PMID 40700071, 2025). "Diabetes was defined as fasting plasma glucose of at least 7.0 mmol/l, self-reported diabetes diagnosis, or use of insulin or oral hypoglycemic drugs." (PMID 39862247, 2025). "Our research corroborated a decline in m6A modification levels post-intensive insulin therapy among people with diabetes." (PMID 40299682, 2025). "Suboptimal insulin injection is widely used to treat Chinese patients with diabetes, with most patients being treated in primary care institutions." (PMID 40900896, 2025). "Type 2 diabetes mellitus (T2DM) is a chronic metabolic disorder characterized by the body's inability to effectively utilize insulin, resulting in elevated blood glucose levels." (PMID 41337811, 2025).